PHB1 (prohibitin 1)
Diseases named in the same sentence as PHB1 in open-access papers (continued):
Sharing a sentence is not in itself a finding about the gene and the disease.
inflammatory bowel disease (4 papers, 2012 to 2025). A spectrum of small and large bowel inflammatory diseases of unknown etiology. "Alteration of PHB1 expression is associated with various diseases including cancer, inflammatory bowel diseases, obesity, cholestatic liver diseases, and neurodegenerative diseases including Parkinson’s and Alzheimer’s disease." (PMID 36593241, 2023). "The levels of Phb1 mRNA and protein were found to be lower in the inflamed mucosa of individuals with inflammatory bowel disease (IBD) as well as in experimental models of colitis." (PMID 33175859, 2020).
liver fibrosis (4 papers, 2015 to 2023). "Diseases and biofunctions analyses conducted by IPA verified that hepatic system diseases, including liver fibrosis, liver hyperplasia/hyperproliferation, and liver necrosis/cell death, which may be caused by hepatotoxicity, were highly associated with liver-specific Phb1 deficiency in mice." (PMID 34539442, 2021). "Furthermore, prohibitin 1 plays an important role in the formation of fibrosis, as liver-specific Phb1−/− mice spontaneously develop liver fibrosis." (PMID 38332916, 2023).
myocardial infarction (4 papers, 2015 to 2021). Gross necrosis of the myocardium, as a result of interruption of the blood supply to the area, as in coronary thrombosis. "Recently, in cardiomyocytes, a study showed that miR-361 initiates mitochondrial fission, with consequent apoptosis leading to myocardial infarction, through the suppression of PHB1 translation." (PMID 30669391, 2019). "Heart-specific PHB1-transgenic mice show low levels of apoptosis and mitochondrial fission in the heart, and consequently, a smaller myocardial infarction size after an experimental infarction." (PMID 26536361, 2015). "Studies in cardiac-specific PHB1 transgenic mice and miRNA361 transgenic mice suggest that the over-expression of miR-361 in response to myocardial infarction surgery reduces the translation of PHB1, favoring mitochondrial fission and myocardial infarction sizes." (PMID 30669391, 2019). "MiR-361,miR-539, and miR-421 inhibit prohibitin 1 (PHB1), PHB2, and PINK1, respectively, to intensify mitochondrial fragmentation and promote H2O2-induced cardiomyocyte apoptosis and myocardial infarction." (PMID 34122082, 2021). "In cardiomyocytes, forced expression of PHB1 attenuated mitochondrial fission and apoptosis induced by H2O2, and cardiac-specific PHB1 transgenic mice showed reduced mitochondrial fission and myocardial infarction sizes after myocardial infarction injury." (PMID 26091791, 2015).
non-small cell lung carcinoma (3 papers, 2023 to 2024). A group of at least three distinct histological types of lung cancer, including non-small cell squamous cell carcinoma, adenocarcinoma, and large cell carcinoma. "Among them, we learned that Bemcentinib has been currently studied for the treatment of non-small cell lung cancer, and the analysis results showed that Bemcentinib can bind to multiple ubiquitination sites (K202, K128, K177) of PHB1 with superior affinity (≤ -7)." (PMID 37359543, 2023).
Parkinson disease (3 papers, 2019 to 2023). A progressive degenerative disorder of the central nervous system characterized by loss of dopamine producing neurons in the substantia nigra and the presence of Lewy bodies in the substantia nigra and locus coeruleus. "Decreased PHB1 and PHB2 expression is associated with aging and age-associated diseases with known mitophagy impairment including Parkinson’s disease and Alzheimer’s disease." (PMID 36593241, 2023).
type 2 diabetes (3 papers, 2019 to 2024). "Although increasing PHB1 levels helps reduce the effects of type 2 diabetes, it does not seem to be because PHB1 levels are lower in people with type 2 diabetes than in people who do not have type 2 diabetes." (PMID 34868199, 2021).
cholangiocarcinoma (2 papers, 2015 to 2019). A carcinoma that arises from the intrahepatic biliary tree (intrahepatic cholangiocarcinoma) or from the junction, or adjacent to the junction, of the right and left hepatic ducts (hilar cholangiocarcinoma).
Crohn disease (2 papers, 2013 to 2023). A gastrointestinal disorder characterized by chronic inflammation involving all layers of the intestinal wall, noncaseating granulomas affecting the intestinal wall and regional lymph nodes, and transmural fibrosis. "PHB1 and NIX co-localization in ileal crypts of Crohn’s disease patients (average 27 ileal crypts/patient across 6 patients) or non-IBD control patients (average 47 ileal crypts/patient across 6 patients) was visualized and quantitated by immunofluorescent staining (arrows)." (PMID 36593241, 2023).
demyelinating peripheral neuropathy (2 papers, 2021). "Here, we show that, contrary to deletion of Phb2, deletion of Phb1 in SCs causes only a minimal developmental phenotype, but triggers a severe demyelinating peripheral neuropathy after myelination is completed." (PMID 34078899, 2021). "We recently showed that conditional ablation of the mitochondrial protein Prohibitin 1 (PHB1) in SCs causes a severe and fast progressing demyelinating peripheral neuropathy in mice, but the mechanism that causes failure of myelin maintenance remained unknown." (PMID 34519641, 2021). "We found that ablation of Phb1 from SCs leads to a mild developmental delay in myelination followed by a severe and progressive demyelinating peripheral neuropathy." (PMID 34078899, 2021).
frontotemporal dementia (2 papers, 2017 to 2021). Frontotemporal dementia (FTD) comprises a group of neurodegenerative disorders, characterized by progressive changes in behavior, executive dysfunction and language impairment, as a result of degeneration of the medial prefrontal and frontoinsular cortices. "Phb2 showed a specific up-regulation in mixed dementia, while Phb1 isoforms were down-regulated in frontotemporal lobar degeneration (FTLD)." (PMID 28831118, 2017).
gallbladder cancer (2 papers, 2018). "Overexpression of PHB1 was verified in gallbladder cancer tissues, and further studies identified that PHB1 promotes cancer cell proliferation by activating ERK and downstream signaling pathways." (PMID 29784973, 2018).
gynecologic cancer (2 papers, 2022 to 2023).
Hepatic steatosis (2 papers, 2021 to 2025). Steatosis is a term used to denote lipid accumulation within hepatocytes. "Because our previous study showed that the Pparγ mRNA expression level, one of the markers of hepatic steatosis, was increased in normal murine hepatocytes transfected with siPhb1, which mimics liver-specific Phb1−/− (unpublished data, under review)." (PMID 34539442, 2021). "We discover that Phb1/2 is an important transcription coregulator in the process of ethanol metabolism, and one identified fatty acid metabolism enzyme Acsl1/5, whose inhibition protects cells and mice from lipid accumulation, a key symptom of hepatic steatosis." (PMID 40858584, 2025).
myeloid tumor (2 papers, 2017 to 2023). "PHB1 and PHB2 proteins are overexpressed in lymphoid and myeloid tumor cell lines compared with healthy donor PBMCs (peripheral blood mononuclear cells)." (PMID 37190120, 2023).
nasopharyngeal carcinoma (2 papers, 2018 to 2019). A carcinoma arising from the nasopharyngeal epithelium. "To further confirm the relationship of LPLUNC1 and PHB1 in NPC tissues, we analysed the mRNA levels of LPLUNC1 and PHB1 in nasopharyngeal carcinoma (NPC) and normal nasopharyngeal epithelium (NPE) by qRT-PCR." (PMID 30886235, 2019).
urothelial carcinoma (2 papers, 2018 to 2020). A malignant neoplasm derived from the transitional epithelium of the urinary tract (urinary bladder, ureter, urethra, or renal pelvis). "It was shown that in urothelial carcinoma cells, FL3 can directly binds to Prohibitin 1 (PHB) preventing its phosphorylation by Akt, leading to a decrease of PHB in mitochondria, which causes a mitochondria-related apoptosis and cell cycle inhibition." (PMID 32792639, 2020).
alcohol use disorder (1 paper, 2025). "Additionally, Phb1, an analogue of Phb1l2, has been implicated in mediating glutamatergic and dopaminergic neural transmission and becomes dysregulated in several disorders, including alcohol use disorder." (PMID 40000848, 2025).
atherosclerosis (1 paper, 2025). A disease characterized by the build-up of fatty material and calcium deposition in the arterial wall resulting in partial or complete occlusion of the arterial lumen. "However, the expression and biological functions of PHB1/PHB2 in atherosclerosis (AS) remain unclear." (PMID 40168274, 2025).
autosomal dominant optic atrophy (1 paper, 2026). An autosomal dominant hereditary condition characterized by optic atrophy and progressive visual loss. "We present initial evidence that PHB1 is a novel candidate gene potentially associated with dominant optic atrophy or a related mitochondrial disorder." (PMID 42067999, 2026). "We report a novel candidate heterozygous variant in the PHB1 (Prohibitin 1) gene in a large family affected by autosomal dominant optic atrophy." (PMID 42067999, 2026).
cardiomyopathy (1 paper, 2023). A disease of the heart muscle or myocardium proper. "Although prohibitin 1 (PHB1) overexpression was found to attenuate sepsis-related cardiomyopathy through restoring the activity of the mitochondrial respiratory chain 33, 34, evidence for the precise role of PHB2 in endotoxemia-related myocardial depression is still lacking." (PMID 37781037, 2023).
cervical adenocarcinoma (1 paper, 2017). An adenocarcinoma arising from the cervical epithelium. "Moreover, phosphorylation of PHB1 at T258 on the plasma membrane activates PI3K/AKT and the Ras/Raf/MEK/ERK pathways promoting proliferation and metastasis of cancer cells in lung and cervical adenocarcinoma cell lines." (PMID 29029444, 2017).
chronic obstructive lung disease (1 paper, 2013). "Abnormal lung bioenergetics has been also reported in smokers (especially in patients with chronic obstructive lung disease and down-regulation of prohibitin-1) and with exposures to particulate matters of aerodynamic diameters of ≤10 μm." (PMID 23311890, 2013).
cutaneous leishmaniasis (1 paper, 2018). Leishmaniasis affecting the skin. "In the present study, we investigate the characteristics and function of prohibitins 1 and 2 (PHB1, PHB2) of Leishmania major, the etiological agent of cutaneous leishmaniasis in the Old World." (PMID 30514373, 2018).
endometriosis (1 paper, 2024). The growth of functional endometrial tissue in anatomic sites outside the uterine body. "Besides, PHB1 is downregulated in the eutopic and ectopic endometrium of patients with endometriosis compared to women without endometriosis." (PMID 38308254, 2024).
head and neck squamous cell carcinoma (1 paper, 2023). A squamous cell carcinoma that arises from any of the following anatomic sites: lip and oral cavity, nasal cavity, paranasal sinuses, pharynx, larynx, and salivary glands. "Prohibitins, PHB1 and PHB2, function as tumor suppressors in head and neck squamous cell carcinomas." (PMID 37190120, 2023).
heart failure (1 paper, 2015). Inability of the heart to pump blood at an adequate rate to meet tissue metabolic requirements. "Because of the importance of STAT3/PHB1 complex in mitochondria as a therapeutic target in heart failure, the effects of flavaglines need to be examined in experimental models of this disease." (PMID 26536361, 2015).
Hepatitis (1 paper, 2022). Inflammation of the liver. "Moreover, IL-6 is associated with the protein level of PHB1 in hepatitis; however, the role of the PHB1/IL-6/STAT3 signalling pathway in the development of hepatitis is controversial." (PMID 35847581, 2022).
hyperlipidemia (1 paper, 2025). "In the present study, an enzyme-linked immunosorbent assay was used to detect PHB1/PHB2 expression in the serum of patients with hyperlipidemia." (PMID 40168274, 2025). "Our in vivo experiments demonstrated increased serum PHB1/PHB2 levels in patients with hyperlipidemia." (PMID 40168274, 2025). "Compared with the healthy subjects, PHB1/PHB2 expression was elevated in the serum of patients with hyperlipidemia." (PMID 40168274, 2025). "In this study, we detected PHB1/PHB2 expression in the serum of patients with hyperlipidemia using ELISA." (PMID 40168274, 2025).
ischemia (1 paper, 2021). A hypoperfusion of the BLOOD through an organ or tissue caused by a PATHOLOGIC CONSTRICTION or obstruction of its BLOOD VESSELS, or an absence of BLOOD CIRCULATION. "Upregulation of PHB1 increases neuroprotection in mice against brain damage from ischemia." (PMID 34868199, 2021).
liver disease (1 paper, 2021). "Through this comparison, DE genes showing greater differences between Phb1+/− and WT may provide sharper perceptions of alteration of physiological responses in a liver-specific Phb1-deficient mouse as a liver disease model." (PMID 34539442, 2021). "Additionally, SREBPs and Pparα may be key genes to elucidate the pathogenesis of liver diseases relevant to Phb1 deficiency in terms of lipid metabolism." (PMID 34539442, 2021). "Further investigations are needed to characterize functional connections between Phb1 and Timp1 in the liver disease model." (PMID 34539442, 2021). "The objective of the present study was to conduct global gene expression analyses of liver-specific Prohibitin 1 (Phb1) knockout (KO) mice as a liver disease model." (PMID 34539442, 2021). "Also, we verified the expression level of hepatic disease-related genes in normal murine hepatocytes transfected with Phb1 siRNA to compare RNA-seq data." (PMID 34539442, 2021). "Interestingly, of liver disease-related 5 DE genes between Phb1+/− and WT, the mRNA expressions of forkhead box M1 (Foxm1) and TIMP inhibitor of metalloproteinase (Timp1) were matched with validation for RNA-seq in liver tissues and AML12 cells transfected with Phb1 siRNA." (PMID 34539442, 2021).
lymphoid tumor (1 paper, 2017). "Taken together, PHB1 and PHB2 were identified to be primarily confined to the mitochondria in lymphoid tumor cell lines, including Kit225 cells." (PMID 29029444, 2017).
lymphoma (1 paper, 2017). A malignant (clonal) proliferation of B- lymphocytes or T- lymphocytes which involves the lymph nodes, bone marrow and/or extranodal sites. "Thus, concordant with prohibitin expression observed in tumor cell lines, PHB1 and PHB2 are overexpressed in lymphoid (T- and B-cell leukemia/lymphoma) and myeloid (CML) primary patient tumor cells." (PMID 29029444, 2017).
malaria (1 paper, 2026). Malaria is a serious and sometimes fatal disease caused by a parasite that commonly infects a certain type of mosquito which feeds on humans. "The human malaria causing parasite Plasmodium falciparum harbors four SPFH proteins, including prohibitin 1 and 2, prohibitin-like protein (PHBL), and stomatin-like protein (STOML), which all localize to the parasite mitochondrion." (PMID 41662436, 2026).
metastatic melanoma (1 paper, 2017). A melanoma that has spread from its primary site to another anatomic site. "We investigated the regulation of PHB1 by miR-195 and its possible impact on chemoresistance of metastatic melanoma cell lines harboring a BRAF-V600E mutation." (PMID 29126391, 2017).
ovarian tumor (1 paper, 2022).
primary biliary cholangitis (1 paper, 2023). Primary biliary cholangitis (PBC) is a chronic and slowly progressive cholestatic liver disease of autoimmune etiology characterized by injury of the intrahepatic bile ducts that may eventually lead to liver failure. "Notably, prohibitin 1 is downregulated in the liver tissue of people with primary biliary cholangitis (PBC), an immune-mediated cholestatic liver disease where defective biliary bicarbonate secretion may play a pathogenic role." (PMID 38332916, 2023).
primary sclerosing cholangitis (1 paper, 2023). "Anti-galectin-3, anti-prohibitin 1 and 2 autoantibody positivity in IRC and healthy and disease (primary sclerosing cholangitis (PSC)) control sera was assessed by ELISA/liquid chromatography–tandem mass spectrometry (LC-MS/MS)." (PMID 38332916, 2023).
promyelocytic leukemia (1 paper, 2025). "Confocal microscopy and immunofluorescence analyses revealed that PHB1 co-localizes with SUMO-1 and accumulates in promyelocytic leukemia nuclear bodies (PML-NBs), stress-responsive subnuclear structures enriched in SUMO-modified proteins." (PMID 40650059, 2025).
pulmonary hypertension (1 paper, 2022). Increased pressure within the pulmonary circulation due to lung or heart disorder. "Similarly, loss of prohibitin 1 in a rat model of pulmonary hypertension showed that the loss of prohibitin 1 resulted in increased high mobility group box 1 (HMGB1)-mediated vascular injury." (PMID 35407523, 2022).
retinal detachment (1 paper, 2011). An eye emergency condition which may lead to blindness if left untreated. "2D-PAGE analysis showed prohibitin 1 to be upregulated following retinal detachment." (PMID 22065916, 2011).
rheumatoid arthritis (1 paper, 2025). A chronic, systemic autoimmune disorder characterized by inflammation in the synovial membranes and articular surfaces. "Prohibitin was used as an inducer in rheumatoid arthritis and as a novel autoantigen in previous studies, suggesting that PHB1 and PHB2 might play a role as secretory proteins." (PMID 40168274, 2025).
Right ventricular cardiomyopathy (1 paper, 2020). Right ventricular dysfunction (global or regional) with functional and morphological right ventricular abnormalities, with or without left ventricular disease. "The pathways involved in the antagonistic GSK-126 group were the bacterial invasion of epithelial cell pathway and the arrhythmogenic right ventricular cardiomyopathy (ARVC) pathway, involving proteins of the PSMD family such as CTNNB1, CTNNA1, PHB1, and SUCLG2." (PMID 33195195, 2020).
SARS-CoV infections (1 paper, 2023). "A previous study by Cornillez-Ty and colleagues reported that NSP2 interacts with prohibitin 1 (PHB1) and PHB2 and may be involved in the disruption of intracellular host signaling during SARS-CoV infections." (PMID 38132484, 2023).
thyroid tumor (1 paper, 2018). A benign or malignant neoplasm affecting the thyroid gland. "The expression of PHB1 was found to significantly increase in the thyroid tumor cells treated with trichostatin A (TSA) and sodium butyrate (NaB), two histone deacetylase inhibitors, demonstrating that HDAC1/2 regulates both PHB1 transcription and alternative splicing." (PMID 29784973, 2018).
urothelial carcinoma of the bladder (1 paper, 2018). "Prohibitin 1 (PHB) is a potential target for the treatment of urothelial carcinoma of the bladder (UCB)." (PMID 29415747, 2018).